EGFR (epidermal growth factor receptor)
Diseases named in the same sentence as EGFR in open-access papers (continued):
Sharing a sentence is not in itself a finding about the gene and the disease.
colon carcinoma (continued). "EGFR expression has been shown to be associated with negative prognostic factors for DFS and OS, and with postoperative recurrence in stage III colon cancer." (PMID 36497002, 2022). "The epidermal growth factor receptor/extracellular signal-regulated kinase signal pathway activation influences the onset and progression of colon cancer by upregulating the expression level of ANO1 in colon cancer." (PMID 36518255, 2022). "In conclusion, anti-EGFR monoclonal antibodies administered as a monotherapy have a substantial clinical effect in colon cancer, improving the survival of patients without K-RAS, N-RAS, or H-RAS mutations, commonly known as wild-type patients." (PMID 36005935, 2022). "EGFR has previously been shown to elevate LD numbers in human colon cancer cells and we found that both EGFR and PI3κ, but not PLA2 were the driving force behind the induction of LDs following viral infection." (PMID 34527863, 2021). "The analysis of a Phase III trial of panitumumab (PICCOLO) reported similar PFS outcomes between rectal and right-sided colon cancers in RAS-wt mCRC patients and mentioned that the benefit of anti-EGFR agents against rectal cancers may be overestimated." (PMID 34188197, 2021). "In H508 colon cancer cells, inhibiting Src attenuated ACh- and EGF-induced ERK1/2 phosphorylation (activation), identifying Src as a key link between M3R-induced transactivation of EGFR and the subsequent downstream activation of MAPK (ERK1/2) in CRC." (PMID 33450835, 2021). "Moreover, PI3K is one of the EGFR targets, and the abnormality of PI3K/AKT signaling pathway is considered to be related to the onset of UC, as well as UC-induced colon cancer." (PMID 34177580, 2021). "Recently, the primary tumor location (PTL) has been validated as a response predictor of anti-EGFR mAb, whose benefit is mainly seen in patients of left-sided but not right-sided colonic tumors." (PMID 34012917, 2021). "Indeed, we recently found that in addition to blocking cullin neddylation as a potent NAE inhibitor, MLN4924 also activates EGFR and downstream AKT1 and ERK1/2 signals by triggering EGFR dimerization in lung, breast and colon cancer cells." (PMID 33263949, 2021). "Similarly, EGFR inhibition with PD153035 and erlotinib reduced the cell death of colon carcinoma cells under hypoxic conditions compared to the vehicle control." (PMID 33092032, 2020). "In colon carcinoma cells, the consequences of EGFR blockade in hypoxia (e.g., induced by bevacizumab) have not been evaluated yet." (PMID 33092032, 2020). "Besides, CXCL12 can trigger anti-apoptotic and proliferative signals in colon cancer cells by inducing mononuclear phagocytes to release HB-EGF, which binds the Epidermal Growth Factor Receptor (EGFR/HER1) and stimulates its signaling." (PMID 33363463, 2020). "Although all three phase III trials evaluating EGFR inhibition in mEGC failed to achieve their primary endpoints, EGFR biomarker analysis suggests that as in lung and colon cancers, EGFR inhibition has a significant role in a properly selected population." (PMID 33364187, 2020). "In maximal settings, for patients with left-sided colon cancer and known KRAS/NRAS wild type (WT) molecular status, anti-EGFR antibodies such as cetuximab or panitumumab may be added to chemotherapy doublet, with a moderate-strength recommendation." (PMID 32150483, 2020). "The four colon cancer cell lines without any alteration in the EGFR pathway (i.e., E705, DIFI, MICOL24, CACO-2), as well as the normal mucosa cell line, were treated with cetuximab in order to evaluate the effect of this drug." (PMID 33233823, 2020). "Interestingly, EGFR can also activate the Ras–Raf–MEK–ERK signaling pathway in colon cancer, which accelerates the progression and development of colon cancer." (PMID 32149326, 2020).
colon carcinoma (continued). "The third sensitive colon cancer cell line, E705, showed that EGFR phosphorylation was not affected by NEU3 transfection, and cetuximab acted on cell viability regardless of NEU3 transfection." (PMID 33233823, 2020). "Previously, we have described the nanobody-PS or VHH-PS conjugates specifically targeting the epidermal growth factor receptor (EGFR), a receptor tyrosine kinase (RTK) that is found overexpressed on a large variety of cancers, such as head and neck, lung, or colon cancer." (PMID 31544832, 2019). "Here we report that the newly synthesized β-phenylacrylic acid derivatives, MHY791 and MHY1036 (MHYs), bind to epidermal growth factor receptor (EGFR) tyrosine kinase domains and function as EGFR inhibitors, having anti-cancer activities selectively in wild-type KRAS colon cancer." (PMID 30158525, 2018). "We generate CAR T cells targeting the epidermal growth factor receptor variant III and measure their tumor killing effects against colon cancer cells with or without miR-153 overexpression by killing assays and in xenografts." (PMID 29685162, 2018). "Colon cancer cells were exposed to EGF for three-time intervals and then pretreated with the membrane-impermeable chemical cross-linker BS3 allowing resolution of dimeric components of EGFR." (PMID 29499765, 2018). "Others have shown that decreased ST6Gal1 may increase EGF-induced EGFR phosphorylation and ERK1/2 activation in colon cancer cells." (PMID 30187356, 2018). "BRAF (V600E) mutant colon cancers may benefit from a combination therapy consisting of BRAF and EGFR inhibitors; EGFR and BRAF (V600E) inhibitors synergize to induce apoptosis of colorectal cells and to suppress colorectal tumor growth in a xenograft model." (PMID 28499452, 2017). "To further expand this panel of human colon cancer cell lines, we have selected other two CRC cells, sensitive to EGFR blockade, such as CACO2 and LIM1215, to generate by an in vitro selection new models of acquired resistance to cetuximab (CACO2-CR and LIM1215-CR)." (PMID 28978055, 2017). "And its activity occurs through the regulation of different signaling pathways like β-catenin/Tcf or AMP-activated protein kinase (AMPK) in colon cancer cells, NF-κB and AP-1/JNK in human hepatoma cells, or EGFR/PI3K/Akt pathway in prostate cancer and EGFR in liver cells." (PMID 28740570, 2017). "Prior research has also reported that the mRNA expression levels of EGFR does not significantly differ between right- and left-sided colon cancers." (PMID 29383110, 2017). "Cetuximab, an EGFR antibody, has been approved by the FDA for the treatment of colon cancer with wild-type KRAS, but not those with a KRAS mutation, and for the treatment of certain stages of head and neck cancer." (PMID 28125617, 2017). "Although the difference in OS was not significant between the patients with right- and left-sided colon cancers, OS tended to be more favorable in the patients with negative EGFR expression than in those with positive EGFR expression." (PMID 29383110, 2017). "Considering that the presence of mutations in KRAS gene renders tumor cells inherently resistant to anti-EGFR therapy, our results indicate that miR-143 or miR-145 may be key players in mitigating cetuximab resistance in mutant KRAS colon cancer cells." (PMID 26824186, 2016). "Rapid Akt activation by vemurafenib has also been shown in colon cancer cell lines, due to constitutive EGFR expression and the relief of negative feedback by the drug." (PMID 27342992, 2016). "For instance, the 5-FU sensitivity of HT29 colon cancer cells was increased in the presence of 0.5 μM PFL, a concentration that was not harmful to the cells, although the effect of PFL was limited compared with EGFR drugs." (PMID 26850110, 2016).
colon carcinoma (continued). "Colon cancer cells with and without oncogenic mutations such as KRAS and BRAF mutations were treated with erlotinib, an inhibitor of epidermal growth factor receptor, in order to detect the impact of these mutations on Raman spectra of the cells." (PMID 26168967, 2015). "A negative feedback loop from ERK to the EGFR has already been proposed previously in colon cancer cell lines with mutant BRAF, where ERK phosphorylation induced the activation of a CDC25C phosphatase, which in turn can dephosphorylate and inhibit the EGFR." (PMID 26065894, 2015). "Our results indicate that HSP90 and EGFR could be used as biomarkers for treatment response monitoring during AT13387 therapy in HNSCC and colon cancer." (PMID 26452257, 2015). "In colon cancer cells, initial reduction in ERK signaling by BRAFV600E inhibitor treatment decreases the phosphatase activity of CDC25C, which in turn results in elevated EGFR phosphorylation." (PMID 26023796, 2015). "Finally, protein levels of members of the HER receptor family such as EGFR and HER3 were analysed in HGUE-C-1 and others colon cancer cell lines." (PMID 25885658, 2015). "Similar results were observed in both RCC cell lines after treatment with DIM-C-pPhOH or DIM-C-pPhCO2Me, confirming that the NR4A1 antagonists inhibited NR4A1-regulated expression of survivin, bcl-2 and EGFR in ACHN and 786-O cells as previously reported in pancreatic, lung and colon cancers." (PMID 26035713, 2015). "In colon cancer the disruption of the negative feedback loop from ERK to the EGFR confers resistance to RAF inhibitor drugs and promotes transformation despite RAF inhibition." (PMID 26065894, 2015). "It provided a new therapeutic strategy in colon cancer by blocking AQP3 and EGFR pathway." (PMID 25886458, 2015). "Our results suggest that heterodimer formation of EGFR and HER-4 may play an important role in the tumourigenesis of colon cancer and contribute to faster disease relapse in these patients." (PMID 24609222, 2014). "Furthermore, targeting Pim-1 sensitized prostate and colon cancer cells to chemotherapeutic agents, and improved the efficacy of AKT inhibitors and epidermal growth factor receptor (EGFR) targeted therapies in prostate cancer." (PMID 25342548, 2014). "We applied a limited candidate gene approach (EGFR, HGF ad MET by immunohistochemistry), array CGH, and genomic sequencing to compare CB42 to other propagation-incapable, β-Catenin-driven primary colon tumors to identify a series of candidate genes that correlated with propagation/metastasis." (PMID 25162504, 2014). "Similarly, in acquired cetuximab-resistant colon cancer cells, overexpression of TGF-α induced the EGFR-MET interaction with subsequent MET phosphorylation, which contributed to cetuximab resistance." (PMID 24714091, 2014). "Moreover, signaling through EGFR and HER3 is thought to play a role in colon cancer and HER3 expression has been shown to correlate disease progression in colon cancer patients." (PMID 25400118, 2014). "Increased levels of HER3 mRNA in colon cancer cell lines and colorectal tumors have been reported and HER3 expression can be detected in 30-90% of colorectal tumors where HER3 is frequently co-expressed with HER2 and EGFR." (PMID 25400118, 2014). "In conclusion, the present study did not confirm correlations between tissue mRNA levels and protein content of COX-1 and EGFR, while a weak correlation was observed between the 74 kDa COX-2 protein and COX-2 mRNA in colon cancer tissue, accounting for tumor stage." (PMID 24171795, 2013). "Suppression of EGFR expression and inhibition of receptor tyrosine phosphorylation of EGFR interrupts EGF signaling, which collectively contributes to the inhibition of colon cancer cell growth by curcumin." (PMID 23251236, 2013). "Therapeutic interventions that are designed to block EGFR signaling in TGFα-positive colon tumors will likely have a negative impact on a number of processes that are essential for metastasis formation." (PMID 23986907, 2013).
colon carcinoma (continued). "Moreover, in colon cancer cells, PAR1 and PAR2 induce migratory and proliferative effects that involve transactivation of the EGFR and activation of p42/p44 MAPK signalling pathways." (PMID 24215724, 2013). "Convincing data on colon carcinoma will be demonstrated at ESMO 2012 with the conclusion to screen patients for BRAFV600E for enrolment in an upcoming clinical trial combining BRAF and EGFR inhibitors." (PMID 23006938, 2012). "Furthermore, consistent with our current data in HNSCC, we have previously shown, in both cell culture and animal models of colon cancer, that PEG-induced EGFR downregulation suppressed proliferation potentially through cyclin D1." (PMID 22675506, 2012). "In stably-transfected human colon cancer cells, overexpression of FXR reduced EGFR, ERK, Src phosphorylation and cell proliferation, and in nude mice attenuated the growth of human colon cancer xenografts (64% reduction in tumor volume; 47% reduction in tumor weight; both P<0.01)." (PMID 23119029, 2012). "Moreover combined knockdown of Sp1, Sp3 and Sp4 using an oligonucleotide cocktail (iSp) also decreased expression of p65, PTTG-1, EGFR and cyclin D1 in RKO cells confirming their regulation by Sp transcription factors in colon cancer cells." (PMID 21864401, 2011). "Moreover, a recent study in a model of colitis-associated colon cancer showed that ginseng reduced levels of phospho-active EGFR and phospho-active ErbB2 as well as ERK, a down stream effector of EGFR, indicating ginseng could suppress EGFR signals in colonic tumorigenesis." (PMID 22070864, 2011). "In conclusion, phospho-EGFR expression was detected in 40% of stage II and III colon carcinomas." (PMID 19997103, 2010). "EGFR (epidermal growth factor receptor) amplification, for instance, is a marker for gefitinib treatment and TYMS (thymidylate synthase) amplification conveys 5-fluorouracil resistance in colon tumors." (PMID 20398377, 2010). "The KRAS mutation also serves as a strong predictor of non-responsiveness to EGFR–targeted agents in lung and colon cancers." (PMID 21124782, 2010). "Till date, the prognostic effect of phospho-EGFR expression in human colon cancers has not been addressed." (PMID 19997103, 2010). "Recently, elongation of a microsatellite repeat at the 5′ UTR was found in colon cancers with defective MMR, but not in those with intact MMR, and elongation of this repeat was associated with downregulation of EGFR mRNA levels." (PMID 19997103, 2010). "Several large randomized-controlled trials demonstrated no benefit from expensive anti-EGFR drugs such as cetuximab (ErbituxTM) in patients with KRAS-mutant colon cancer." (PMID 21110880, 2010). "Recently, it has been shown that EGFR-negative colon tumours have the potential to respond to cetuximab-based therapies." (PMID 19654571, 2009). "EGF treatment rapidly induced phosphorylation of both EGFR and ERK1/2 in HT29 colon cancer cells." (PMID 16138927, 2005). "Moreover, in mismatch repair-proficient BRAF-V600E-mutant colon cancers, combined EGFR and BRAF/MEK therapy is not cross-resistant with standard chemotherapy, suggesting new rational combination treatment strategies." (PMID 39626159, 2024). "Furthermore, the overabundance of ZKSCAN3 correlates with elevated levels of several factors that contribute to colon cancer progression, including integrin, cyclin D1 (CCND1), epidermal growth factor receptor (EGFR), and vascular endothelial growth factor (VEGF)." (PMID 39519085, 2024). "It is unclear if these gene markers could play a role in EGFR and COX pathways to colon cancer." (PMID 38609520, 2024). "A study focused on the TME in colon cancer observed that co-culturing macrophages with colon cancer cells stimulated the release of epidermal growth factor (EGF) in CRC cells, which activated the EGFR/PI3K/AKT/mTOR signaling pathways, resulting in a polarization of TAMs into M2 phenotype." (PMID 35912261, 2022).
colon carcinoma (continued). "For example, in human colon cancer cell lines SNU-C4, HT-29, and H508, administration of atropine, muscarinic receptors inhibitor eradicated SNU-C4 cell migration and HT-29 invasion; however, H508 cell migration entails the activation of MMP7 via EGFR and ERK signaling pathways." (PMID 36614038, 2022). "Experiments on human colon cancer cells in vitro have revealed that metastatic cells may express up to five times more EGFR than nonmetastatic cells." (PMID 35409206, 2022). "Competitive binding studies using three cell lines with different EGFR expression showed that conjugate 5 specifically binds to colon cancer cells overexpressing EGFR (HT-29), while non-specific binding was also observed in cells with low EGFR expression (LOVO)." (PMID 33498632, 2021). "Blockage of the EGFR signaling pathway present in cancerous cells has been shown to assist in M2 macrophage polarization, reduced tumor growth and showed a reduction in the amount of infiltrating CD206+ M2 macrophages in AOM/DSS-induced murine colon cancer mice." (PMID 34063667, 2021). "Data from the first-line setting further suggest that an EGFR-based first-line therapy might create a favorable precondition for second-line treatments with VEGF-targeted antibodies, particularly in left-sided colon cancer." (PMID 32429380, 2020). "In the murine APCmin/+ model of colon cancer, it was established that the genetic deletion of ADAM17, which is responsible for generating not only sIL-6R but also soluble TNFα and soluble ligands of the epidermal growth factor receptor (EGFR), resulted in completely abrogated tumour development." (PMID 32864098, 2020). "High EGFR expression is said to be found in 25–77% of colon cancers and 90% or more of HNSCC, when ligands such as EGF and transforming growth factor-α (TGF-α) bind to EGFR, they form a dimer with EGFR or other human epidermal growth factor receptor (HER) family members." (PMID 33383632, 2020). "On the contrary, HER2-amplified colon cancer cells were resistant to all anti-EGFR inhibitors, expanding and confirming the results from previous studies regarding the role of HER2 amplification in either primary and acquired resistance to EGFR targeted therapies." (PMID 31164152, 2019). "For example, colon cancers that have a normally functioning version of a surface protein called KRAS are likely to respond to certain anti-epidermal growth factor receptor (EGFR) antibody therapies; those in which the protein is absent or non-functional are not." (PMID 30231499, 2018). "Given that the pro-apoptotic effect of MHYs on colon cancer cells is derived by the Src/JNK signaling axis, it is reasonable to speculate that inhibition of EGFR and activation of the Src/JNK signaling pathway appear to cooperatively participate in enhancing the cell death." (PMID 30158525, 2018). "Key evidence from colon cancer suggests that BRAF (V600E)-mutant tumors are not responsive to vemurafenib alone but only in combination with an EGFR inhibitor to repress the rapid feedback activation of EGFR by vemurafenib treatment." (PMID 29503809, 2018). "Thus, inhibition of EGFR signaling by monoclonal antibodies (i.e., Cetuximab) or tyrosine kinase inhibitors (TKi; i.e., gefitinib or erlotinib) is synergistic with BRAF inhibition in colon carcinoma cells." (PMID 29033690, 2017). "We found 10 EGFR mutated NSCLC (6 with short in-frame deletions of exon 19 and 4 cases with single-nucleotide substitutions in exon 21 characterized by the missense mutation p.L858R); and, 7 KRAS mutated colon carcinomas [data not tabled]." (PMID 28099523, 2017). "Therefore, we used EGFR-negative colon cancer cell lines SW620 and HT-29 as control target cells in the following experiments." (PMID 29423418, 2017).